MMP2 (matrix metallopeptidase 2)
Diseases named in the same sentence as MMP2 in open-access papers (continued):
Sharing a sentence is not in itself a finding about the gene and the disease.
tumor (continued). "Evidence from past literature demonstrates that SPHK1 enhances the production of MMP-2 and MMP-9 and thereby promotes tumor proliferation and invasion of colon cancer." (PMID 36309544, 2022). "Low expression of miR-138-5p in tumors leads to overexpression of HOXD11, which induced FN1 transcription and increased MMP2 and MMP9 expression to degrade ECM and promoted tumor metastasis in vivo and in vitro." (PMID 36151071, 2022). "In this study, prodrug vesicles underwent a charge transformation at tumor tissue by the MMP-2-triggered cleavage of PEG-PS conjugates, which not only enhanced the cellular uptake and deep tumor penetration, but also selectively released the PS." (PMID 34987658, 2022). "Low expression of MMP-2 in patients with different grades indicates remission of AML patients, reduced differentiation of tumor cells, and fewer complications." (PMID 35935313, 2022). "Supplementing conjugated linoleic acid decreased the levels of TNF-α, IL-1β, hsCRP, MMP-2 and MMP-9, which are biomarkers of tumor aggression and angiogenesis." (PMID 36776395, 2022). "We assessed the expression levels of candidate invasion-specific protein biomarkers CTSK, MMP9, MMP2, TIMP2, and PTTG1 by immunohistochemical staining in paraffin-embedded NFPA tumor tissues." (PMID 36052250, 2022). "Proteolytic enzyme MMP2 and MMP9 facilitate cell invasion and migration by degrading the extracellular matrix (ECM), thereby allowing the invasion of tumor cells into adjacent tissues and the subsequent migration of cells into circulation." (PMID 35889537, 2022). "Matrix metalloproteinase-2 (MMP-2) is a collagenase that plays a role in tissue regeneration, angiogenesis, inflammation, tumor metastasis and wound healing." (PMID 35269967, 2022). "Scientific evidence revealed that several proteases as MMP2 and MMP9 are involved in many steps of cancer, including primary tumor growth, angiogenesis, invasion of the basement membrane and stroma, and metastatic process." (PMID 36430394, 2022). "Taken together, the fluorescence imaging and CLSM examination data verified increased tumour accumulation and penetration of the PGDA7 NPs via MMP-2-mediated cleavage of the PEG corona." (PMID 35882867, 2022). "The inhibition of SIRT1 decreases the Matrix metalloproteinase 2 (MMP2) and FOXO3a expression in MCF-7 cells which participate in apoptosis and tumor invasion." (PMID 36552538, 2022). "Crucially, MMP2 and MMP9 expression is often upregulated in tumours and their degradation of components like proteoglycans can release bound bioactive components termed matrikines or matricryptins." (PMID 36045675, 2022). "The nanosystem AuNPs@pep1/pep2 includes the substrate peptide PLGVRGDD to identify the presence of MMP-2, an RGD motif for tumor detection, while peptide two functions as an assembly-activated scaffold." (PMID 36230480, 2022). "MMP-2 and MMP-9 are more critical for angiogenesis than for ECM degradation, which are considered to be the key to promoting tumor angiogenesis." (PMID 36065269, 2022). "Because component changes in ECM induce EMT, MMP2 and MMP9 can also induce and promote EMT to promote tumour progression." (PMID 36408277, 2022). "In summary, cross‐talk between tumor cells and CAFs increased succinylated FBN1 and MMP2 expression and promoted tumor cell invasion into the stroma." (PMID 35901491, 2022). "Members of the MMP family, MMP2 and MMP9, play a key role in tumour invasion, metastasis and angiogenesis." (PMID 35000605, 2022). "Invadopodia can secret matrix metalloproteinases (MMPs) characterized by MMP2 and MMP9 to remodel the ECM and enhance tumor cell motility 32,33." (PMID 36147460, 2022). "In previous papers, some tumor-promoting genes (like Snail1, Slug, ZEB1/2, MMP2, MMP9, and ADAM12) were found to be modulated by TGF-β." (PMID 35794983, 2022).
tumor (continued). "Currently, MMPs are recognized as the most important enzymes for ECM degradation, and in particular, the abnormal expression of MMP-2 and MMP-9 can lead to accelerated tumor progression." (PMID 36432106, 2022). "Ascitic fluid from OC patients containing high levels of MMP-2 and VEGF induced an increase in the invasive and angiogenic activity of tumor cells in vitro." (PMID 35682890, 2022). "HOXD11 was mediated by miR-138-5p and induced FN1 transcription and increased MMP2 and MMP9 expression to degrade ECM and promoted tumor metastasis in vivo and in vitro." (PMID 36151071, 2022). "MTX is linked to DEX by a peptide that can be cleaved by matrix-metalloproteinase-2 (MMP-2) and matrix-metalloproteinase-9 (MMP-9), two important enzymes present in tumor tissue." (PMID 36145522, 2022). "Proteolytic enzymes MMP-2 and MMP-9 are overexpressed in cancer, resulting in increased tumor migration and invasion." (PMID 35875198, 2022). "By binding to transmembrane proteins (αβ integrins, CD44, EGF receptor/EGFR), MMP2 and MMP9 directly trigger intracellular signalling pathways that control tumour cell events." (PMID 35158891, 2022). "Experiments showed that the downregulation of FOXM1 reduced the expression and function of the matrix metalloproteinase-2/9 (MMP-2/9) and vascular endothelial growth factor (VEGF), leading to the inhibition of tumor invasion, migration, and angiogenesis." (PMID 35646056, 2022). "Together, these findings oppose a crucial role of MMP-9 and MMP-2 in the observed combined effects of CXCL12 and CXCL11 on tumor cell invasion." (PMID 36539774, 2022). "After transfection of tumor-derived DNA, the expression of CXCL12-CXCR4 axis, P-ERK1/2, and MMP2/9 proteins was further significantly increased under CXCR4 overexpression." (PMID 35860597, 2022). "Related research findings found that downregulation of FOXP3 inhibited tumor cell invasion by reducing MMP-9 and MMP-2." (PMID 36185217, 2022). "MMP2 can degrade the basement membrane, and MMP9 can induce tumor cells to infiltrate and migrate to surrounding tissues along the damaged basement membrane." (PMID 35468097, 2022). "The synergistic activation of these MMPs modulators only induces an additive reduction of the MMP-2 and MMP-9 activities, suggesting MMPs should be a critical control point for the ability of lung metastasis of the xenografted tumor." (PMID 35711540, 2022). "MMP-2 and MMP-9 catalyze the degradation of most extracellular matrix and basement membrane components and promote tumor angiogenesis, thereby enhancing tumor invasion and metastasis." (PMID 36276736, 2022). "Quantitative RT-PCR and gelatin zymography demonstrated low to medium expression levels of MMP-2 and/or MMP-9 in some tumor cells and their absence in others." (PMID 36539774, 2022). "The angiogenic factors for VEGF-C and MMP2 were assessed with in vivo evaluation of the nanosystem upon ENT release and tumor necrosis in nude mice with a KYSE-30 cell xenograft." (PMID 35337150, 2022). "Correspondingly, LDH-C4 can be induced by EMT and the expression of MMP-2 and MMP-9 to achieve xenograft tumor growth and metastatic potential by the activation of the PI3K/AKT pathway in vivo." (PMID 36408133, 2022). "Previous studies demonstrated that STAT3 can directly or indirectly interact with the promoters of cyclin D1, Twist, MMP2, MMP7, MMP9, VEGF, upregulate their expression and regulate cell proliferation, tumor metastasis and angiogenesis." (PMID 36295083, 2022). "MMPs, in particular MMP-2, MMP-9 and MMP-14,57 facilitate tissue remodelling, a vital process during neo-angiogenesis and tumour progression." (PMID 33758004, 2022). "CAFs and tumor-associated macrophages (TAMs) also produce a metalloproteinase named MMP2 to remodel ECM production and composition, thereby resulting in tumor cell invasion, progression, and metastasis, while supporting angiogenesis." (PMID 36553542, 2022).
tumor (continued). "Crucially, MT1-MMP and MMP9 activity can release extracellular heparin-bound VEGF which can induce MMP2 and MMP9 expression from tumour cells, likely via VEGFR2 activation." (PMID 36045675, 2022). "As evidenced by IHC staining, the expression levels of KIF20A, MMP-2, MMP-9 and MKI67 increased significantly in tumor tissues in the KDELR2 overexpression group." (PMID 36096734, 2022). "Another tumor secretome released in an autophagy-dependent manner includes growth factors (TGF-β1, b-FGF), extracellular matrix proteins (MMP2, MMP9) and the angiogenesis stimulant (VEGFA)." (PMID 36160153, 2022). "In the invasive tumor group we found two significant positive correlations: first between MMP-1 and MMP-2 expression (rho = 0.306, p = 0.031) and second between TIMP-2 and MMP-9 expression (rho = 0.464, p = 0.001)." (PMID 36551933, 2022). "Invasion is an important feature of malignant tumors, and MMP2 and MMP9 are the most widely studied matrix metalloproteinases that play important roles in tumor cell invasion and metastasis." (PMID 35898928, 2022). "MMP2 and MMP9 can hydrolyse basement membrane components and regulate various aspects of tumour growth and metastasis." (PMID 36408277, 2022). "Matrix metalloproteinase 2 (MMP2) and Matrix metalloproteinase 9 (MMP9) are important for tumor cell proliferation." (PMID 35672776, 2022). "Matrix metallopeptidase 2 (MMP2) belongs to the matrix metalloproteinase family, which can degrade the tumor-mediated extracellular matrix." (PMID 36463205, 2022). "In the presence of matrix metalloproteinase 2(MMP2), DOX and AP were quickly released from AP-PP-DOX, with the released DOX showing excellent anti-tumor efficacy." (PMID 35664731, 2022). "MMP-2 together with MMP-9, are the two most common progression markers correlated with invasion and metastasis in various tumor, especially HCC15,16." (PMID 35948625, 2022). "The nanovesicle comprised a matrix metalloproteinase 2 (MMP‐2)‐sheddable polyethylene glycol (PEG) corona to improve tumor‐specific accumulation and deep tumor penetration." (PMID 36344430, 2022). "In liver cancer cells, mRNA expression of MMP-2 and MMP-9 is up-regulated as a result of the inhibition of miR-21, which stimulates the invasion and migration of tumor cells." (PMID 36776395, 2022). "In vivo experiments confirmed that higher-dose bevacizumab facilitated metastasis in tumor-bearing nude mice and upregulated the expression of RGC32, N-cadherin, and MMP2, whereas anlotinib abrogated its effect." (PMID 35664796, 2022). "Other signaling molecules such as MAPK, MMP2/9, CYP and ROS are also involved in the anti-cancer effects by regulating the tumor microenvironment, cancer metastasis, carcinogen metabolism and oxidation." (PMID 35736173, 2022). "It was recently reported that S100A4 enhanced the expression of mouse SAA1 and SAA3, which stimulated expression of RANTES, G-CSF, MMP2, S100A8, and S100A9 to promote tumor metastasis." (PMID 35936690, 2022). "These reported significantly higher concentrations of mainly MMP-1, MMP-2, MMP-3 and MMP-9, but also of other MMPs in the saliva of patients with OSCC, compared to healthy controls, which were also correlated with the tumor stage." (PMID 36547091, 2022). "MMP-2 and MMP-9 are expressed in cancer cells that degrade the extracellular matrix (ECM) type IV collagen during tumor metastasis and invasion." (PMID 35355732, 2022). "Matrix metalloproteinases (MMPs), including MMP2 and MMP9, have been previously reported to promote cell migration and tumour metastasis." (PMID 35811356, 2022). "In PCa, MMP-2 and MMP-9 are relevant molecular biomarkers that reflect the tumor’s invasive and metastatic potential." (PMID 35669415, 2022). "This study also suggested that FOXP3 can upregulate the expression of MMP2 and MMP9, both of which play a promoting role in tumor metastasis." (PMID 36235242, 2022). "Thus, the tumor-promotive function of KDELR2 on MMP2 and MMP9 might be tissue/cell-specific." (PMID 36096734, 2022).
tumor (continued). "The results of research are consistent with the conclusion that MMP-2 index increased with the increase of risk coefficient, which may be due to the fact that MMP-2 has the important function of decomposing matrix membrane, which can regulate the growth of tumor cells." (PMID 35935313, 2022). "In a mouse model of tumor invasion, macrophages infiltrate and express MT1-MMP, resulting in activation of MMP-2 and consequent inhibition of TGF-β." (PMID 36776395, 2022). "Tumor cells can primarily express MMP-2 and MMP-9 to debase type IV collagens and disrupt these tissue barriers, which stimulates tumor cell invasion and metastasis." (PMID 35747793, 2022). "It has been reported that p‐AKT activation is crucial in HCC progression, and MMP2 and MMP9 are involved in tumour invasion and metastasis." (PMID 35811356, 2022). "In BCC's stroma and the peritumoral area, CAFs can secrete an array of MMPs (e.g., MMP-1, MMP-2, MMP-3, MMP-9, MMP-11, MMP-13, MMP-14, MMP-19), all of them promoting ECM remodeling and favoring tumor escape from the anti-tumoral action of the immune cells." (PMID 35572966, 2022). "MMP-2 and MMP-9 can degrade the ECM, greatly change the viscosity and mobility of the tumor, and promote invasion and metastasis." (PMID 35684565, 2022). "Curcumin downregulated NF-κB and FAK/P38 MAPK and reduced the expression of VEGF, MMP-2, MMP-9, and COX-2 to exert the anti-tumor angiogenesis attribute in vivo and in vitro." (PMID 35784750, 2022). "We first examined the expression of MMP2 and MMP9 in G401 cells and mouse tumour-bearing tissues after intervention with DCH." (PMID 36408277, 2022). "Matrix metalloproteinases MMP2 and MMP9 can induce the degradation of extracellular matrix components, promoting tumor cell infiltration and spread in the bloodstream." (PMID 35893303, 2022). "BB94 is a potent extracellular broad-spectrum MMP inhibitor that inhibits MMP-1, MMP-2, MMP-3, MMP-7, and MMP-9 and distant tumor metastases." (PMID 35440570, 2022). "The matrix metalloproteinases (MMPs) including MMP-2 and MMP-9 belong to a family of proteinases that can catalyze the cleavage of extracellular matrix components, thus favoring tumor cell migration, invasion, and metastasis." (PMID 36177059, 2022). "This acidification drives the increased expression and activation of matrix metalloproteases (MMP2 and MMP9), which proteolytically cleaves extracellular matrix proteins driving matrix degradation and tumor cell invasion." (PMID 35686673, 2022). "Among the members of MMP family proteins, MMP-2 and MMP-9 are considered to play important roles in the metastasis of tumor cells." (PMID 36483979, 2022). "MMP-2 and MMP-9, also known as Gelatinase A and B, respectively, play critical roles in tumor cell invasion and metastasis, as they can degrade the major components of the extracellular matrix (ECM), a major component of the tumor microenvironment." (PMID 36611945, 2022). "We additionally determined the activity of matrix metalloproteases (MMP2 and MMP9), since MMPs are critical for tumor invasion in many types of cancer, including GBM." (PMID 35682709, 2022). "Our study showed that circMYC is highly expressed in SCLC tumor, which is required to support the malignant phenotype of SCLC cells by promoting the expression of MMP2." (PMID 35441564, 2022). "Ionizing radiation has been shown to alter tumor microenvironment by interfering cell-cell communication and inducing stromal cells to secrete various cytokines, ɑ-SMA, MMP-2 and MMP-9, which can potentially promote the metastasis of cancer." (PMID 36084485, 2022). "In this study, the MMP‐2‐sensitive peptide and flexible peptide were inserted between the FTH1 and TmSm proteins, enabling the release of the TmSm protein at the tumor site." (PMID 35600646, 2022). "Activated STAT3 can directly bind to the promoter of MMP2 and VEGF to upregulate their expression, thus promoting tumor metastasis and angiogenesis." (PMID 36295083, 2022).
tumor (continued). "An unconventional CAR is the Chlorotoxin (CLTX) peptide-based CAR shown to bind a variety of GBM cell lines and primary GBM that express MMP-2 and to be efficacious in orthotopic xenograft GBM tumour models." (PMID 35454848, 2022). "In the case of papillary RCC, MMP-2 expression was positively correlated with patient age (p < 0.05), while CD44 expression was positively correlated with tumor stage (τ = 0.26, p < 0.05)." (PMID 36079127, 2022). "Multiple MMP family members, such as collagenase 1 (MMP-1), gelatinase A (MMP-2), gelatinase B (MMP-9), matrilysin (MMP-7), and membrane-type (MT)-MMPs, have been correlated with tumor progression such as the formation of metastasis and bad prognosis." (PMID 36366531, 2022). "When comparing the gene profile of CAFs from two tumor foci for each one of these cases, we only found significant differences between CAFs populations for FGF10, IL17RB, and MMP2, evidencing a little variability within the multifocal PCa tumor focus." (PMID 35885510, 2022). "MMP-2 and MMP-9 are zymogens that are secreted primarily by tumor cells and stromal cells and play an essential role in extracellular matrix degradation, tumor invasion, and metastasis." (PMID 35875198, 2022). "Numerous studies demonstrated that MIF has been involved in the migration and invasion of cancer cells by up-regulating the pro-metastatic mediators MMPs, among which MMP2 and MMP9 degrades the ECM and facilitates the tumor cell invasion and metastasis." (PMID 36703790, 2022). "IHC assay presented that the expression of Ki67, MMP2 and MMP9 was strikingly lower in sh-circ-CSNK1G1-administered tumor tissues relative to sh-NC, suggesting the growth of tumor tissues was suppressed by sh-circ-CSNK1G1." (PMID 36109751, 2022). "Data showed that MMP2 and MMP9 expression was positively correlated to tumour invasion depth, venous invasion and increased tumour size (over 4cm)." (PMID 36045675, 2022). "Our results showed that RAB26 silence reduced the expression of Ki67, PCNA, MMP2 and MMP7 in xenograft tumor samples, suggesting the suppression of RAB26 silence on NSCLC growth and metastasis in vivo." (PMID 35291909, 2022). "MMP-2 and MMP-9 are recognized as major contributors to the proteolytic degradation of extracellular matrix during tumor invasion." (PMID 35953439, 2022). "A matrix metalloproteinase-2 (MMP-2)-activatable probe was constructed using Cy5 dye to monitor and visualize tumor-induced lymphangiogenesis." (PMID 35682614, 2022). "Recent studies have demonstrated that FN1 activates matrix metalloproteinase 2 (MMP2) and MMP9 expression to hydrolyze components of the basement membrane and thus can promote tumor invasion and metastasis in various cancers." (PMID 36151071, 2022). "In the non-invasive tumor group there was only one significant correlation, between TIMP-2 and MMP-2 expression (rho = 0.378, p = 0.039)." (PMID 36551933, 2022). "After being activated by GM-CSF, GAMs can release the chemokine C-C ligand 5 (CCL5) to upregulate MMP2 secretion in GBM cells, consequently promoting tumor migration and invasion." (PMID 36013403, 2022). "The high expression of MMP-2 enzyme in the tumor tissues cleaved the peptide GPLGVRG between G and V and removed the TPGS3350 outer layer, making it easier to penetrate the tumor site." (PMID 36077102, 2022). "High TGFβ expression within the tumor microenvironment was also reported as important in the induction of MMP-2 and MMP-9 proteins in both tumor and endothelial cells, promoting invasion and angiogenesis." (PMID 36497429, 2022). "Among MMPs, MMP-2 and MMP-9 have drawn much attention for their implication in tumor invasion and metastasis." (PMID 35887021, 2022). "We validated this possibility in G401 cells and the tumour tissues of MRTK and confirmed the high expression levels of MMP2 and MMP9 in MRTK." (PMID 36408277, 2022).